REN (renin)
Diseases named in the same sentence as REN in open-access papers (continued):
Sharing a sentence is not in itself a finding about the gene and the disease.
Hypertension (continued). "Renin is related to vasoconstriction because of angiotensin, which is converted from angiotensinogen by renin, so the regulation of renin activity is important to hypertension patients." (PMID 31480566, 2019). "AMPKα2 knockout mice expressed activation of the renin-angiotensin system (RAS) to favor the development of hypertension." (PMID 31443482, 2019). "Angiotensinogen (AGT), the initial substrate of the renin-angiotensin-aldosterone system pathway, is involved in the development of hypertension in humans and other animals." (PMID 30700972, 2019). "Younger people with mild essential hypertension commonly have high renin hypertension due to elevated renal sympathetic activity which results in greater secretion of renin." (PMID 31920690, 2019). "In low-protein diet model, adult male offspring developed low nephron number and hypertension, which is related to renal hyperfiltration and activation of the renin–angiotensin system (RAS)." (PMID 31010060, 2019). "At the same time, angiotensin II increases the expression of NADPH oxidase and the generation of ROS, potential mediators of some renin-angiotensin-induced hypertension effects." (PMID 31261912, 2019). "TNF-α propagates renal damage during hypertension induced by activation of the renin–angiotensin system as well as exacerbates the severity of renal disease and poring overall outcomes and survival rates amongst the CKD patients." (PMID 30617956, 2019). "Previously, dietary polyunsaturated fatty acids have been thought to explain the possible relationship between metabolites and hypertension through regulation of the renin-angiotensin II system." (PMID 31426326, 2019). "VDD+AmB/LE rats also presented alterations in the PTH-Klotho-FGF-23 signaling axis, urinary concentrating defect and hypertension, probably due to an inappropriate activation of the renin-angiotensin-aldosterone system." (PMID 31295336, 2019). "Ghrelin is able to block the renin-angiotensin system improving hypertension and cardiovascular disorders." (PMID 31694146, 2019). "PA is characterized by at least partially autonomous aldosterone production (despite low renin levels), hypertension and low or normal serum potassium levels." (PMID 31695023, 2019). "Decreased level of BDNF is observed in depression and its connection to hypertension has also been demonstrated with affecting the arterial baroreceptors, renin–angiotensin system and endothelial nitric oxide synthase." (PMID 30767081, 2019). "Hyperuricemia leads to hypertension and renal injury via a crystal-independent mechanism by stimulating the renin–angiotensin system and inhibiting neuronal nitric oxide synthase." (PMID 31126092, 2019). "When female transgenic mice carrying the human AGT gene were mated with male mice carrying the human REN gene, they developed preeclampsia (hypertension and proteinuria) in mid-gestation." (PMID 31551925, 2019). "Several mechanisms are involved in the pathogenesis of obesity-induced hypertension, including adipokine release, insulin resistance, and stimulation of sympathetic nervous system and renin-angiotensin system." (PMID 31888029, 2019). "Nevertheless, our finding is important because it provides further rationale for initial treatment of hypertension with the renin-angiotensin-aldosterone system (RAAS) blockade, in view of the well-established antiproteinuric effects." (PMID 31243534, 2019). "They demonstrated that such pups exhibited hypertension and increased renal expression of renin and AT1 receptor." (PMID 31380328, 2019). "All forms of monogenic hypertension have low renin and can be further classified by the levels of aldosterone." (PMID 31312622, 2019). "All components of the renin-angiotensin system are present within the CNS, and local production of brain Ang II is now well accepted to contribute to the development of hypertension at old age." (PMID 31329158, 2019).
Hypertension (continued). "This vascular remodeling seems to be influenced by hemodynamic factors such as hypertension and most often can be reversed at least in part by pharmacological blockade of the renin-angiotensin-aldosterone or endothelin systems." (PMID 30837878, 2019). "Renin levels in hypertension seem to differ with age, and the discovery and validation cohorts differed in age by decades." (PMID 31581667, 2019). "Many different pathophysiologic mechanisms result in hypertension, but renin-angiotensin-aldosterone system (RAAS) activation plays an important role." (PMID 31214554, 2019). "Several physiological mechanisms link vitamin D to hypertension because calcitriol acts as an endogenous inhibitor of the Renin-Angiotensin System." (PMID 31315602, 2019). "Basic characteristics of this disease are hypertension, reduced concentration of aldosterone and renin activity, as well as increased excretion of potassium leading to low level of potassium in serum and metabolic alkalosis." (PMID 31655555, 2019). "AGT is an important substrate of the renin–angiotensin–aldosterone system and an important target in hypertension research." (PMID 31649728, 2019). "Increased production of aldosterone drives the key clinical features of hypertension and hypokalemia in the setting of suppressed renin levels." (PMID 31312622, 2019). "Hypertension and T2DM also share common pathways such as those associated with the sympathetic nervous system (SNS) and renin-angiotensin-aldosterone system (RAAS)." (PMID 31032243, 2019). "Aliskiren hemifumarate (AHF) is the first clinically approved, orally active, highly potent, and selective renin inhibitor for the treatment of hypertension alone or in combination with other antihypertensive agents." (PMID 31374890, 2019). "The activity of renin can be inhibited by the small molecule Aliskiren, a clinically frequently used compound, which was shown to effectively reduce arterial hypertension, and its sequels, that is nephropathy and myocardial infarction." (PMID 31551909, 2019). "Altogether, these data suggest a possible involvement of the Renin-Angiotensin-Aldosterone System (RAAS) in the arising of hypertension in VDD+AmB/LE rats." (PMID 31295336, 2019). "Early experiments targeted renin for the treatment of hypertension, but few chemical compounds were known to directly and strongly inhibit the function of renin." (PMID 31485348, 2019). "We also cover some recent and relevant discoveries in the field of low-renin hypertension from our laboratory at the National Institutes of Health." (PMID 30832344, 2019). "Adipokines, including adiponectin and leptin, and renin-angiotensin-aldosterone system (RAAS) contribute to hypertension." (PMID 31236708, 2019). "At one month postoperative follow up, PA was biochemically cured in all patients, according to the normalization of the aldosterone/renin ratio and serum potassium levels; hypertension was cured in 10 cases (38%), and improved in the remaining 16 cases (62%)." (PMID 31074381, 2019). "Low renin monogenic hypertension conditions can be further categorized by aldosterone level: low, normal, or high." (PMID 31312622, 2019). "Similar to males, recombinant ACE2 protects female mice against hypertension induced by Ang II infusion or transgenic overexpression of renin." (PMID 31262355, 2019). "The accurate personal history, including a detailed dietary and drug history, and the measurement of renin, aldosterone and serum and urinary electrolytes are necessary for an accurate diagnosis of these forms of hypertension." (PMID 31379750, 2019). "Several genes belong to the renin–angiotensin system have been reported to be altered by epigenetic regulation, culminating to the development of hypertension." (PMID 31010060, 2019). "Base-case scenario for a budget impact analysis of adding drugs that inhibit renin-angiotensin system to standard antihypertensive treatments for patients with hypertension and diabetes in Malaysia." (PMID 30817790, 2019).
Hypertension (continued). "Renal sympathetic activation results in renal vasoconstriction, increased renin secretion, and enhanced sodium and water reabsorption, all of which contribute to the development of hypertension." (PMID 31612099, 2019). "Renin–angiotensin aldosterone inhibitors are considered the mainstay treatment for hypertension in diabetic patients, especially in the presence of albuminuria." (PMID 31315312, 2019). "It is well known that the renin-angiotensin system (RAS) plays a critical role in the development of hypertension and end-organ damage." (PMID 31011475, 2019). "There is evidence that RAAS dysregulation is also involved in essential hypertension since the renin plasma levels differ widely in essential hypertensive patients, and 15% of them have elevation in plasma renin activity." (PMID 31703282, 2019). "Calcium channel blockers (CCBs) and renin–angiotensin system (RAS) inhibitors are recommended as first-line treatment options for patients with hypertension according to the Japanese Society of Hypertension guidelines." (PMID 31554937, 2019). "It is well known that the renin-angiotensin system is activated in most cases of essential hypertension and plays a key role in blood pressure elevation." (PMID 31011475, 2019). "Patients with low renin (i.e., salt-sensitive hypertension) represent approximately 30% of the essential hypertensives, and show a poor therapeutic response to angiotensin-converting enzyme inhibitors and angiotensin receptor blockers." (PMID 31109113, 2019). "Drugs targeting the renin-angiotensin-aldosterone system (RAAS) are cornerstone of the management of hypertension." (PMID 31885897, 2019). "The renin-angiotensin aldosterone system (RAAS) is a peptide hormone system that contributes to various hypertensive disorders (secondary hypertensions), such as renovascular hypertension, malignant hypertension, and renin-secreting neoplasms." (PMID 31703282, 2019). "An increase in patients with hypertension has led to a corresponding increase in the number of patients using renin-angiotensin–aldosterone system inhibitors." (PMID 30039479, 2018). "In diabetic nephropathy, activation of renin-angiotensin system induces hypertension and stimulates NADPH oxidase." (PMID 30210440, 2018). "Lastly, hormonal changes during the peri-menopausal period can bring about metabolic syndrome, but also has effects on the renin-angiotensin system and affects production of angiotensin and sodium metabolism, which in turn can also lead to hypertension." (PMID 30349737, 2018). "Obesity is associated with an increased activity of the sympathetic nervous system, the activation of the renin–angiotensin system, hormonal perturbations, and renal structural damage, which can lead to hypertension." (PMID 28058464, 2018). "Since renin-angiotensin system (RAS) is known to play an important role in the pathophysiology of hypertension, in the present study, we evaluated the gene and protein modulation of RAS after two periods of MEs in a spontaneous hypertensive rat (SHR) model." (PMID 30498455, 2018). "Many situations and medication have effects on kidney functions, such as hypertension, lipid profiles, glycemic variability, and the renin-angiotensin-aldosterone system blockade." (PMID 30538743, 2018). "Dysregulation of the renin-angiotensin system leads to systemic hypertension and maladaptive fibrosis in various organs." (PMID 30576317, 2018). "Resveratrol suppression of angiotensin II-induced hypertension is in part due to inhibited renin–angiotensin system." (PMID 30301188, 2018). "Renin–angiotensin system drugs are very commonly used in diabetes for treating hypertension and micro-albuminuria, and these medicines have been shown to be protective against cognitive impairment." (PMID 30182156, 2018).
Hypertension (continued). "Earlier animal studies demonstrated that vitamin D receptor-null (VDR-null) mice have a several-fold increase in renin expression and plasma angiotensin II production, which leads to hypertension, cardiac hypertrophy and increased water intake." (PMID 29977597, 2018). "For individuals with CKD, pharmacological intervention, such as the use of inhibitors of the renin-angiotensin system to control hypertension and proteinuria, has also been found to be effective in delaying the CKD progression." (PMID 30112209, 2018). "A renin-angiotensin-aldosterone system blocker is recommended in the treatment of hypertension in DM, particularly in the presence of proteinuria or micro-albuminuria." (PMID 29168408, 2018). "The kidney functions in patients with T2D were influence by many situations and medicine, such as hypertension, lipid profiles, glycemic variability, and the renin-angiotensin-aldosterone system blockade." (PMID 30538743, 2018). "Angiotensin II, a key effector of the renin-angiotensin system, plays roles in mediating hypertension, heart failure, and inflammatory responses." (PMID 29590257, 2018). "The most common clinical presentation of the disease is early onset hypertension, hypokalemia, metabolic alkalosis, suppressed plasma renin activity and low plasma aldosterone." (PMID 29534496, 2018). "The superoxide-generating enzyme Nox2 contributes to hypertension and cardiovascular remodeling triggered by activation of the renin-angiotensin system." (PMID 29688896, 2018). "Although the cause of hypertension in Turner syndrome is still not clear, structural etiology as well as heart autonomic innervations, increased plasma renin activity (PRA), and parasympathetic neuropathy, can cause hypertension in Turner syndrome patients." (PMID 29747617, 2018). "Nevertheless, conducted vasodilator responses are intact in Cx37 knockout mice and in animals with an angiotensin-dependent hypertension evoked by deletion of Cx40 in the renin-producing cells." (PMID 29874791, 2018). "The protective effects of prenatal metformin therapy on HFR/HFA-induced hypertension, including downregulation of the renin-angiotensin system, decrease in uric acid level, and reduction of oxidative stress." (PMID 29614026, 2018). "Accumulated evidence has shown that low renin hypertension is common in patients with diabetic nephropathy." (PMID 30332741, 2018). "Pressure overload mainly derives from increased peripheral resistance and reduced arterial compliance due to sympathetic and renin-angiotensin system hyperactivity, hypertension, endothelial dysfunction, and vascular calcification/stiffening." (PMID 30126435, 2018). "RAS inhibitors, including ACE inhibitors, ANG II receptor blockers, and renin inhibitors are commonly used in the treatment of hypertension." (PMID 29540174, 2018). "Second, UA can lead to endothelial dysfunction and induce hypertension through activation of the renin-angiotensin system." (PMID 30400636, 2018). "In the later phase (after 8 weeks), the plasma renin activity and AngII levels are reduced, but the hypertension is maintained." (PMID 29590257, 2018). "Hypertension is a progressive disease involving abnormalities in the renin-angiotensin-sympathetic interactions." (PMID 30510587, 2018). "Despite this highly evolved physiology, low-renin hypertension (LRH) is currently a prevalent biochemical phenotype described in up to 30% of hypertensives, depending on age and race." (PMID 29439489, 2018). "The composite of evidence suggests that the LRH is likely a heterogeneous admixture of disease states that all converge on a phenotype of suppressed renin activity and high blood pressure." (PMID 29439489, 2018). "20-HETE is involved with the renin-angiotensin system to promote hypertension, vasoconstriction, and vascular dysfunction." (PMID 28056085, 2017).
Hypertension (continued). "Obesity is linked to increased sympathetic nervous system activation and increased renin release, which are thought to contribute to hypertension development in obese individuals." (PMID 28932747, 2017). "Alterations in the renin-angiotensin system (RAS) are a major contributor to hypertension, and changes to the renal RAS occur following a range of in utero perturbations." (PMID 28811528, 2017). "Due to his persistent hypokalaemia, hypertension and supressed renin and aldosterone levels, sequencing of exon 13 of the beta-chain of the epithelial sodium channel was pursued." (PMID 29144530, 2017). "Individualized therapy for hypertension based on phenotyping with plasma renin and aldosterone markedly improves blood pressure control in patients with resistant hypertension." (PMID 28721209, 2017). "The renin-angiotensin-aldosterone system (RAAS) plays a key role in the pathophysiology of arterial hypertension as well as in more complex mechanisms of cardiovascular and renal diseases." (PMID 28598381, 2017). "Another limitation was common ACE-I and ARBs use in hypertension or congestive heart failure treatment with its influence on renin-angiotensin-aldosterone axis inhibition." (PMID 28710615, 2017). "Renin showed an expression decrease that preceded the onset of hypertension in the autonomic dysfunction phenotype." (PMID 28732007, 2017). "So, in addition to its direct vasoconstricting effects, increased SNS activity also leads to elevated BP and hypertension by increasing renin–angiotensin–aldosterone system (RAAS) activity." (PMID 28993801, 2017). "Omega-3 PUFA ethyl-esters (25 g/kg diet) or a direct renin inhibitor (aliskiren; 3 mg/kg/day) reduced arrhythmia induction, from 75% to 17%, vs. 0% in rats suffering from high renin-induced hypertension." (PMID 29084142, 2017). "Many of the patients in our study were in early stages of hypertension, and 61 (31%) had undetectable plasma aldosterone and renin." (PMID 29119005, 2017). "Diabetes is often accompanied by hypertension and these two conditions share conjunct pathways such as the renin-angiotensin aldosterone system, the sympathetic nervous system, adipokines, the inflammatory pathway, and oxidative stress." (PMID 28545089, 2017). "Schaefer concluded that fluid overload, activation of the renin-angiotensin system, sympathetic hyperactivation, endothelial dysfunction and chronic hyperparathyroidism were contributing to CKD-associated hypertension." (PMID 27882810, 2017). "Volume overload and the renin–aldosterone–angiotensin system (RAAS) are 2 major factors contributing to hypertension (HTN) among hemodialysis (HD) patients." (PMID 28383400, 2017). "Recently, a new receptor was discovered, able to bind renin and prorenin and increase the conversion of angiotensinogen to Ang I, but its role in hypertension and pharmacological renin inhibition remains to be clarified." (PMID 28598381, 2017). "OC gets a high score in CODA as it impacts on renin in both microtubules and mesangial cells of kidney and renin is connected to hypertension in kidney." (PMID 28790372, 2017). "Elevation of uric acid due to uricase inhibitor had been reported to induce thickening of afferent arteriole, renin-angiotensin system activation, and hypertension in rats." (PMID 29089036, 2017). "Raising levels of uric acid also had been reported to occur in rats with administration of uricase inhibitor and led to thickening of afferent arteriole, activation of the renin-angiotensin system, and hypertension." (PMID 29089036, 2017). "This was aided by the initiation in 1977 of a hypertension clinic basing the management of resistant hypertension on levels of stimulated plasma renin activity." (PMID 28721209, 2017). "Even before reading the text in detail, it is easy to see that “renin” and “hypertension” both appear frequently, indicating that they are important." (PMID 28153818, 2017).